GRB2 (growth factor receptor bound protein 2)
Diseases named in the same sentence as GRB2 in open-access papers (continued):
Sharing a sentence is not in itself a finding about the gene and the disease.
carotid atherosclerosis (2 papers, 2022 to 2024). A thickening and loss of elasticity of the walls of carotid arteries that occur with formation of atherosclerotic plaques. "Serum GRB2 was found to be positively correlated with C-reactive protein and interleukin-6 levels, which were higher in patients with T2DM (compared to the healthy population), and further increased in patients with T2DM with carotid atherosclerosis." (PMID 39408563, 2024).
COVID-19 (2 papers, 2023 to 2025). A disease caused by infection with severe acute respiratory syndrome coronavirus 2. "GRB2 has been identified as a potential drug target in COVID-19 due to its role in inflammatory signaling pathways." (PMID 41325417, 2025). "Growth factor receptor-bound protein 2 (GBR2) is a receptor for interleukin-6 (IL6), whose serum levels significantly increase in COVID-19 patients." (PMID 36851954, 2023).
fibrosarcoma (2 papers, 2015 to 2021). A malignant mesenchymal fibroblastic neoplasm affecting the soft tissue and bone. "Activation of Tyr 985 is required for triggering rat sarcoma (Ras)/rapidly accelerated fibrosarcoma (Raf)/extracellular signal-regulated kinases 1/2 (ERK1/2) pathways through interaction with an adaptor protein, growth factor receptor-bound protein 2 (GRB2)." (PMID 26376613, 2015).
fibrosis (2 papers, 2016 to 2025). the formation of excess fibrous connective tissue in an organ or tissue in a reparative or reactive process. "GRB2 induces cardiac fibrosis and hypertrophy through the stimulation of the p38 MAPK and JNK pathways." (PMID 39863867, 2025). "They demonstrated inverse relationship between miR-19b and GRB2 expression where miR-19b was down-regulated and GRB2 mRNA was up-regulated in rat fibrosis model with reversal of these effects in estradiol treated rats." (PMID 26999230, 2016).
heart failure (2 papers, 2016 to 2025). Inability of the heart to pump blood at an adequate rate to meet tissue metabolic requirements. "Similarly, GRB2 is a downstream protein in the transforming growth factor beta 1 stimulated myofibroblast transformation process in cardiac fibrosis and heart failure." (PMID 39863867, 2025).
Hepatitis (2 papers, 2010 to 2022). Inflammation of the liver. "Diseases associated with GRB2 include Wiskott‐Aldrich syndrome and hepatitis." (PMID 35212166, 2022). "GRB2 and HSPA1A and B genes directly act on angiogenesis, TAF11 is known to be involved in artery passage, and the E2F1 transcription factor is known to be an angiogenesis positive inducer in hepatitis and cancer." (PMID 20426824, 2010).
Huntington disease (2 papers, 2013 to 2017). Huntington disease (HD) is a rare neurodegenerative disorder of the central nervous system characterized by unwanted choreatic movements, behavioral and psychiatric disturbances and dementia. "We have also reported previously that Grb2 is naturally overexpressed in different neurodegenerative scenarios, specifically Huntington's disease (HD), and that it shows a chaperone-like action there." (PMID 28360125, 2017). "We checked the levels of Grb2 mRNA and protein in age matched R6/2 mouse model of Huntington’s disease." (PMID 24116161, 2013).
Hypertension (2 papers, 2023 to 2024). The presence of chronic increased pressure in the systemic arterial system. "Limited research has been conducted on the function of Grb2 in hypertension." (PMID 38732116, 2024). "Thus, the upregulation of Grb2 could have pathological implications by affecting the cytoskeleton in vascular or cardiac cells, potentially leading to hypertension." (PMID 38732116, 2024).
Insulin resistance (2 papers, 2022 to 2024). Increased resistance towards insulin, that is, diminished effectiveness of insulin in reducing blood glucose levels. "Furthermore, serum GRB2 concentrations are linked to glucolipid metabolism, inflammatory variables, and insulin resistance, and more research is needed in the future to determine the possible pathophysiological function of GRB2 in T2DM with CAS." (PMID 36176460, 2022).
myocardial infarction (2 papers, 2023 to 2025). Gross necrosis of the myocardium, as a result of interruption of the blood supply to the area, as in coronary thrombosis. "The microRNA-378a/GRB2 pathway can promote cardiac fibrosis via lncRNAs in the myocardial infarction model." (PMID 39863867, 2025).
neuroendocrine neoplasm (2 papers, 2016 to 2018). Endocrine tumors, also referred to as neuroendocrine tumors (NETs), are defined by a common phenotype which is characterized by the expression of general markers (neuron specific enolase, chromogranin, synaptophysin) and hormone secretion products. "ACTB, CDKN1B, GAPDH, GRB2, RHOA and SDCBP are potent reference genes in neuroendocrine tumors of the lung." (PMID 27802291, 2016). "In the present study, ACTB, CDKN1B, GAPDH, GRB2, RHOA and SDCBP were identified as suitable reference genes in neuroendocrine tumors of the lung." (PMID 27802291, 2016).
Noonan syndrome (2 papers, 2014 to 2018). Noonan Syndrome (NS) is characterized by short stature, typical facial dysmorphism and congenital heart defects. "Grb2 and Sos1 function interdependently on each other, thus, mutations on Sos1 or unusual phosphorylation on Grb2 would lead to aberrant physiological events such as Noonan syndrome and tumorigenesis." (PMID 24775912, 2014).
Obesity (2 papers, 2020 to 2023). Accumulation of substantial excess body fat. "GRb2 has been used to manage atherosclerosis, insulin resistance and obesity, endothelial cell senescence, and suppression of glutamate-induced neurotoxicity." (PMID 38139116, 2023). "Thus, GRb2 appears to have potential for treating diabetes, obesity, tumors, viral infections, and cardiovascular conditions." (PMID 38139116, 2023).
osteosarcoma (2 papers, 2022). A usually aggressive malignant bone-forming mesenchymal neoplasm, predominantly affecting adolescents and young adults. "Whether EID3 maintains the stemness of osteosarcoma cells by upregulating the expression of GRB2 and activating PI3K-AKT pathway remains to be further explored." (PMID 36071872, 2022).
pulmonary arterial hypertension (2 papers, 2020). Pulmonary arterial hypertension (PAH) is a group of diseases characterized by mean pulmonary artery pressure >20 mmHg and elevated pulmonary arterial resistance leading to right heart failure. "The ERK2/GRB2/Shc pathway is critical in vascular smooth muscle cell proliferation, and this indicates that differential expression of hsa-miR-124-3p might be involved in the pathogenesis of pulmonary artery hypertension in patients with COPD." (PMID 32647120, 2020).
sarcoma (2 papers, 2021). A usually aggressive malignant neoplasm of the soft tissue or bone. "On the other hand, the phosphorylated IGF1R can also induce the recruitment of SHC adaptor protein (Shc), growth factor receptor-bound protein 2 (Grb2), Son of Sevenless (SOS), and rat sarcoma (Ras), which leads to stimulate the mitogen activated protein kinase (MAPK) signalling pathway." (PMID 33498859, 2021).
uterine cancer (2 papers, 2020 to 2024). Primary or metastatic malignant neoplasm involving the uterine corpus and/or the cervix. "Downregulating Grb2 protein expression via treatment with L-Grb2 is a promising molecular therapy for ovarian and uterine cancer using a target previously thought to be undruggable." (PMID 32754300, 2020). "In the present study, we tested the anticancer effects of an ASO that blocks Grb2 protein expression incorporated into a neutral liposome (L-Grb2) in preclinical models of ovarian and uterine carcinoma." (PMID 32754300, 2020). "Next we sought to determine the role of Grb2 in uterine cancer models." (PMID 32754300, 2020).
viral infection (2 papers, 2012 to 2022). "In the case of Vaccinia, Nck and Grb2 work together in a signalling network that induces Arp2/3 complex-dependent actin polymerisation to enhance the spread of viral infection." (PMID 35796545, 2022). "However, while Nck function is required to nucleate actin tails, Grb2 was rather found to play a secondary stabilizing role, being itself unable to induce actin reorganization in the host cell during virus infection." (PMID 23226445, 2012).
acute kidney injury (1 paper, 2024). Sudden and sustained deterioration of the kidney function characterized by decreased glomerular filtration rate, increased serum creatinine or oliguria. "Proteomic analysis revealed that Grb2 is involved in myocardial damage following acute kidney injury." (PMID 38732116, 2024).
acute pancreatitis (1 paper, 2025). An acute inflammatory process that leads to necrosis of the pancreatic parenchyma. "To explore the role of Grb2 in vivo, we established a classic acute pancreatitis model using caerulein and treat with the Grb2 inhibitor prexigebersen at 0h." (PMID 40491924, 2025). "We further verified in another PDL model, and the results showed that Grb2 inhibitorprexigebersen also alleviated the severity of PDL-induced acute pancreatitis." (PMID 40491924, 2025).
allergic disease (1 paper, 2021). An immune response that occurs following re-exposure to an innocuous antigen, and that requires the presence of existing antibodies against that antigen. "Several studies have shown the important effects of GRB2 in eosinophils, mast cells and T cells in allergic diseases." (PMID 34589519, 2021).
atherosclerosis (1 paper, 2022). A disease characterized by the build-up of fatty material and calcium deposition in the arterial wall resulting in partial or complete occlusion of the arterial lumen. "An animal study showed that downregulation of GRB2 inhibited the activation of PI3K/AKT/NF-kB pathway which improved lipid accumulation and inflammatory infiltration in rats with atherosclerosis (AS), resulting in an anti-AS effect." (PMID 36176460, 2022).
cardiac interstitial fibrosis (1 paper, 2018). "Interestingly, miR-200a negatively regulates levels of the GRB2 protein by directly binding to the grb2 3′UTR, which, in turn, inhibits the EndMT in a cardiac interstitial fibrosis model." (PMID 29540674, 2018).
chloroma (1 paper, 2021). "The backward elimination procedure identified RUNX1T1, MAPK3, PIK3CG, TCF7L1, GRB2, and MTOR as the empirical drivers of the association with chloroma." (PMID 33882829, 2021).
depression (1 paper, 2023). "Meanwhile, antidepressant drugs may exert beneficial effects on the insulin receptor phosphorylation pathway through the Shc1/Grb2 complex, which further supports the potential use of Sch1 for depression drug development." (PMID 37649561, 2023).
endothelial dysfunction (1 paper, 2021). In vascular diseases, endothelial dysfunction is a systemic pathological state of the endothelium (the inner lining of blood vessels) and can be broadly defined as an imbalance between vasodilating and vasoconstricting substances produced by (or acting on) the endothelium. "The expression of Grb2 was also reduced, eventually causing endothelial dysfunction." (PMID 34326776, 2021).
Granuloma (1 paper, 2019). A compact, organized collection of mature mononuclear phagocytes, which may be but is not necessarily accompanied by accessory features such as necrosis. "Among the enrichment score-driving critical genes of the TCR signaling, the levels of transcripts for ITK and its signaling components such as LCK, GRB2, SLP76, NCK1, FYN, and PLCG are significantly upregulated in caseated granulomas compared to uninvolved lung tissue." (PMID 32038633, 2019).
gynecologic cancer (1 paper, 2020). "In the present study, we examined the biological effects of liposomal antisense oligodeoxynucleotide that blocks Grb2 expression (L-Grb2) in gynecologic cancer models." (PMID 32754300, 2020).
Hepatic steatosis (1 paper, 2016). Steatosis is a term used to denote lipid accumulation within hepatocytes. "The decrease in GRB2 improves hepatic steatosis and glucose metabolism and reduces oxidative stress." (PMID 27594973, 2016).
Hepatitis C (1 paper, 2021). "Another gene in the hsa04550 pathway, GRB2, coding for Growth Factor Receptor Bound Protein 2, is associated with Hepatitis C and Hepatitis E. In turn, Calmodulin-activated adenylate cyclases (ADCY1 and ADCY8 genes) generate cAMP." (PMID 35008650, 2021).
herpesvirus infection (1 paper, 2019). "Notably, GRB2 as well as SOS1 are regulated by non-coding RNAs in other g-herpesvirus infection systems, suggesting this may be a common strategy employed by g-herpesviruses to manipulate RTK signaling." (PMID 30615681, 2019).
Hyperglycemia (1 paper, 2013). An increased concentration of glucose in the blood. "In the current study, increased levels of both long and short forms of leptin receptor, as well as, increased levels of GRB2, phospho-STAT3, and phospho-JAK2 were observed under hyperglycemia." (PMID 24260287, 2013).
inflammatory skin disease (1 paper, 2019). Inflammatory skin disorders covers a broad category that includes many conditions ranging in severity, from mild itching to grave medical health complications These disorders are common in people of all ages and races. "The GRB2 gene is critical in the downstream transduction of EGFR, and the aberrant expression of the latter has been implicated in several inflammatory skin diseases." (PMID 31569353, 2019).
Inguinal hernia (1 paper, 2020). Protrusion of the contents of the abdominal cavity through the inguinal canal. "We discovered that PIK3R1, PTPN11, TGFBR1, CDC42, SOS1, and KRAS were the most essential inguinal hernia-causative proteins and UBC, GRB2, CTNNB1, HSP90AA1, CBL, PLCG1, and CRK were listed as the most commonly-involved downstream proteins." (PMID 31910207, 2020). "Five essential proteins (PIK3R1, PTPN11, TGFBR1, CDC42, and SOS1) and three downstream common proteins (UBC, GRB2, and CTNNB1) were found to be related to inguinal hernia development." (PMID 31910207, 2020). "Most importantly, UBC, GRB2, and CTNNB1 were significantly enriched in the inguinal hernia PPI network." (PMID 31910207, 2020).
insulinoma (1 paper, 2015). "MADD, a splice variant of IG20 (insulinoma-glucagonoma 20) overexpressed in cancer cells, is crucial for RAS/MEK/ERK activation by facilitating recruitment of Grb2 to the receptor-mediated signaling complex." (PMID 26517243, 2015).
invasive breast carcinoma (1 paper, 2020). A carcinoma that infiltrates the breast parenchyma. "Recent studies reported that GRB2 acts as an adaptor protein which plays a central role in the regulation of ARF1 and ARF6 activation in invasive breast cancer." (PMID 32595697, 2020).
mast cell neoplasm (1 paper, 2018). A heterogeneous group of disorders characterized by the abnormal growth and accumulation of mast cells in one or more organ systems. "In conclusion, the present study showed that AQ1 G4-binding compound inhibited KIT expression and its downstream signaling molecules GRB2, AKT and FYN in two in vitro models of human and canine mast cell neoplasms (HMC1.2 and C2 cells)." (PMID 30459395, 2018).
measles (1 paper, 2009). A highly contagious viral infection caused by the measles virus. "We found that hPIV3-C interacts directly through its C-terminal domain with STAT1 and GRB2, whereas C proteins from measles or Nipah viruses failed to do so." (PMID 19806178, 2009).
metastatic cancer (1 paper, 2013). A carcinoma which has spread from the original site of growth to another anatomic site. "Parallel to these observations, we see a drastically reduced interaction on METpY1356 and PTPRApY798 with GRB2 in metastatic cancer cells (MDA-MB231)." (PMID 23826330, 2013).
myeloproliferative disease (1 paper, 2016). "Importantly, such a binding between Grb2 SH2 domain and BCR tyrosine 177 is required for induction of CML-like myeloproliferative disease driven by BCR-ABL in mouse model." (PMID 27329306, 2016).
Nephropathy (1 paper, 2012). A nonspecific term referring to disease or damage of the kidneys. "In order to determine if Grb2 function is required in the response to renal injury, a process for which actin cytoskeleton reorganization is crucial, we injected Grb2flx/flx mice with adriamycin, a chemical that induces nephropathy." (PMID 23226445, 2012).
parasitic infection (1 paper, 2020). "In the up-regulated proteins focal adhesion, various cancers, ECM-receptor interaction, EGFR/GRB2/KRAS (annotated here as dorso-ventral axis formation), and Gap and adherens junctions featured, as did pathways related to bacterial and parasitic infection." (PMID 32161586, 2020).
periodontal disease (1 paper, 2024). "An overexpression of CTNNB1, FOS, JUN, GRB2, PIK3CA, and PIK3R1 may affect the cell cycle, resulting in excessive cell proliferation, and malignant transformation, besides being related to periodontal disease development and progression." (PMID 39517401, 2024).
periodontitis (1 paper, 2020). An acute or chronic inflammatory process that affects the tissues that surround and support the teeth. "Notably, four of the cluster A genes, specifically, CBL, GRB2, PIK3R1, and RELA, were also ranked among the five leader genes previously identified in periodontitis." (PMID 32962181, 2020).
pheochromocytoma (1 paper, 2017). "This is complicated by the fact that while activation of a SOS/Shc-Grb2 complex has been associated with in vitro RIT1 activation following either NGF or PCAP stimulation of pheochromocytoma cells, biochemical analysis has yet to identify a bona fide RIT1GEF." (PMID 28607354, 2017).
Pleural effusion (1 paper, 2022). The presence of an excessive amount of fluid in the pleural cavity. "For comparison with other body fluids (i.e., plasma/serum, BAL, and pleural effusion), 153 out of 912 MV proteins were pleural effusion-specific proteins, including ABI1, BSG, CAV1, GRB2, RAS proteins, and SRC." (PMID 35158999, 2022).
preeclampsia (1 paper, 2012). Preeclampsia is a hypertensive disorder of pregnancy that is characterized by new-onset hypertension with proteinuria presenting after 20 weeks of gestation, and depending on mild or severe forms may initially present with severe headache, visual disturbances, and hyperreflexia. "In this group, EGFR and GRB2, are both with highest scores and there are both well related with preeclampsia." (PMID 22873350, 2012).
psoriasis (1 paper, 2019). An autoimmune condition characterized by red, well-delineated plaques with silvery scales that are usually on the extensor surfaces and scalp. "In the skin network, we identify KDs such as ICAM1, IL15, STAT1, TNFAIP3, and GRB2 to be the network hubs connecting numerous genes in the psoriasis-associated supersets." (PMID 30642337, 2019).
scrapie (1 paper, 2020). A fatal disease of the nervous system in sheep and goats, characterized by pruritus, debility, and locomotor incoordination. "Interestingly, in the brain tissue of scrapie infected rodents, BDNF, TrkB, phospho-TrkB, GRB2 and p75NTR were all significantly down-regulated supporting the direct association identified in our results between GRB2 and p75NTR31,32." (PMID 32917932, 2020).
squamous cell carcinoma (1 paper, 2022). A carcinoma arising from squamous epithelial cells. "The m5C writer NSUN2 was demonstrated to enhance the progression of squamous cell carcinoma by stabilizing LIN28B-dependent GRB2, which could activate the AKT and RTK signaling pathways." (PMID 36246622, 2022).
T cell lymphoma (1 paper, 2023). "GRB2 knockdown and re-expression of selected monomeric and dimeric mutants in a T cell lymphoma cell line led to notable defects in clustering of the adaptor protein LAT and IL-2 release in response to TCR stimulation." (PMID 36864087, 2023).